CCNE2 (cyclin E2)
Diseases named in the same sentence as CCNE2 in open-access papers (continued):
Sharing a sentence is not in itself a finding about the gene and the disease.
leukemia (3 papers, 2021 to 2025). A malignant (clonal) hematologic disorder, involving hematopoietic stem cells and characterized by the presence of primitive or atypical myeloid or lymphoid cells in the bone marrow and the blood. "In addition, we observed downregulation of leukemia-associated proto-oncogenes such as CCND1/2 (0.46, p < 0.05), CCNE2 (0.38 p = 0.0076), MYC (0.42, p < 0.001), SRC (0.3, p < 10−5), or MPL (0.25, p < 0.05)." (PMID 41438051, 2025). "We utilized the data of gene expression profiling in samples with higher E2F1 expression and identified the genes associated with cell cycle progression (CCNA2, CCNE2, CCNB1, CCNB2 and, importantly, CCNE1) which were also found to be upregulated in leukemia cells exposed to DBF." (PMID 34564151, 2021).
nasopharyngeal carcinoma (3 papers, 2019 to 2024). A carcinoma arising from the nasopharyngeal epithelium. "Similarly, miR-150 acted as a tumor suppressor in nasopharyngeal carcinoma to repress cell viability and G1/S phase transition by regulating CCND1 and CCNE2." (PMID 33817286, 2020).
renal carcinoma (3 papers, 2014 to 2017). A carcinoma arising from the epithelium of the renal parenchyma or the renal pelvis. "miR-30d inhibits renal carcinoma cell proliferation via the regulation of cyclin E2 expression at the post-transcriptional level." (PMID 24520297, 2014). "It has been reported that miR-30d may suppress renal carcinoma cell proliferation by regulating cyclin E2 expression at a post-transcriptional level." (PMID 28066696, 2016). "The cyclin E2 gene 3′ UTR reporter vectors, pMIR3’UTR and pcDNA3.1-pre-miR-30d, were co-transfected into the renal carcinoma cells." (PMID 24520297, 2014).
thyroid cancer (3 papers, 2015 to 2022). "In conclusion, our data demonstrate that SOSTDC1 is down-regulated in thyroid tumor tissues and inhibits thyroid cancer cell proliferation through modulating cyclin A2 and cyclin E2." (PMID 26378658, 2015). "Similar with the previous studies, our data demonstrated that decreased cyclin A2 and cyclin E2 were involved in the anti-proliferative role of SOSTDC1 in thyroid cancer." (PMID 26378658, 2015). "The results showed that over-expression of SOSTDC1 in thyroid cancer cells resulted in dys-regulating the expression of critical cell cycle regulators, cyclin A2 and cyclin E2 in vitro and vivo." (PMID 26378658, 2015). "Moreover, our data suggest that SOSTDC1 inhibits the proliferation of thyroid cancer cells via regulation of cyclin A2 and cyclin E2." (PMID 26378658, 2015). "Therefore, SOSTDC1 inhibits the growth of thyroid cancer cells in vivo, likely by decreasing cyclin A2 and cyclin E2." (PMID 26378658, 2015). "Moreover, ectopic over-expression of SOSTDC1 led to down-regulation of cyclin A2 and cyclin E2, which subsequently inhibit thyroid cancer cell proliferation in vitro and in vivo." (PMID 26378658, 2015). "For instance, Cyclin A2 and Cyclin E2 can be mediated by SOSTDC1 and potentiate cell proliferation in thyroid cancer." (PMID 32154226, 2020). "Furthermore, canagliflozin inhibited G1/S phase transition and cyclin D1, cyclin D3, cyclin E1, cyclin E2, and E2F1 expression levels in thyroid cancer cell." (PMID 35148777, 2022).
viral infection (3 papers, 2010 to 2013). "In our previous study we demonstrated that targeting of CCNE2 by US25-1 resulted in reduced cyclin E2 expression and conversely deletion of US25-1 from the virus resulted in increased expression of cyclin E2 in the context of virus infection." (PMID 24385903, 2013). "miR-US25-1 suppressed the expression of a reporter containing the 5' UTR of cyclin E2, whereas deletion of miR-US25-1 from HCMV up-regulates cyclin E2 expression in the context of viral infection." (PMID 21314915, 2011). "Deletion of miR-US25-1 from HCMV results in over expression of cyclin E2 in the context of viral infection." (PMID 20585629, 2010).
acute myeloid leukemia (2 papers, 2015 to 2024). Acute myeloid leukemia (AML) is a group of neoplasms arising from precursor cells committed to the myeloid cell-line differentiation. "In acute myeloid leukemia (AML), Tegaserod can inhibit the translation of cyclin E2 regulated by YTHDF1, thereby affecting the proliferation and survival abilities of AML cells." (PMID 38790013, 2024).
cholangiocarcinoma (2 papers, 2021 to 2022). A carcinoma that arises from the intrahepatic biliary tree (intrahepatic cholangiocarcinoma) or from the junction, or adjacent to the junction, of the right and left hepatic ducts (hilar cholangiocarcinoma).
colon cancer (2 papers, 2014 to 2024). "In conclusion, our study indicates that silencing KCNQ1OT1 in HCT116 and SW480 cells may suppress colon cancer progression by negatively regulating DNA replication and the mitotic cell cycle phase-related pathways, targeting the downstream PCNA and CCNE2." (PMID 38361755, 2024).
endometrial cancer (2 papers, 2021 to 2023). Primary or metastatic malignant neoplasm involving the endometrium (mucous membrane that lines the endometrial cavity). "Finally, we investigated the prognostic impact of CCNE2 CNVs and mRNA expression levels using patient data obtained from the Cancer Genome Atlas-Uterine Corpus Endometrial Carcinoma (TCGA-UCEC) database." (PMID 34885073, 2021).
glioblastoma (2 papers, 2021 to 2024). The most malignant astrocytic tumor (WHO grade IV). "In Msi1 KO glioblastoma cells, we observed that G1-S transition is disrupted, agreeing with an increase in expression of Msi1 targets p21 and p27 and downregulation of CDK2 and CCNE2." (PMID 33804958, 2021).
head and neck squamous cell carcinoma (2 papers, 2017 to 2024). A squamous cell carcinoma that arises from any of the following anatomic sites: lip and oral cavity, nasal cavity, paranasal sinuses, pharynx, larynx, and salivary glands. "ELF3 and CCNE2 presented overexpression patterns in head and neck squamous cell carcinoma." (PMID 39572025, 2024).
HIV-1 infection (2 papers, 2023 to 2025). The type species of lentivirus and the etiologic agent of acquired immunodeficiency syndrome (AIDS). "The CCNE2, as the substrate of CDC4 was reported to act as a dependency factor to induce HIV Tat activity by encoding protein Cyclin E1, Cdk2 and Cyclin E. It is speculated that HIV-1 hijacks CDC4 to sequester it to prevent the degradation of CCNE2, facilitating HIV-1 infection in the target cells." (PMID 40260685, 2025). "It is possible that HIV-1 hijacks FBXW7 to sequester it, thus preventing or co-opting degradation of CCNE2 or one of its other substrates that have no previous implication for HIV-1 infection." (PMID 36744886, 2023).
liver fibrosis (2 papers, 2019 to 2021). "Transition of hepatic stellate cells (HSCs) from a quiescent to an activated state is a sign of the onset of liver fibrosis, and this process is controlled by E-type cyclins (CcnE1, CcnE2) and their associated cyclin-dependent kinase 2 (Cdk2)." (PMID 30923657, 2019). "In good agreement with the published investigations on the role of c-myc, increased expression of Cyclin E1—but not of Cyclin E2 has been shown in human and murine liver fibrosis." (PMID 35087852, 2021). "In contrast, Cyclin E2 was not aberrantly expressed in liver fibrosis at any stage." (PMID 35087852, 2021).
lung adenocarcinoma (2 papers, 2016 to 2020). A carcinoma that arises from the lung and is characterized by the presence of malignant glandular epithelial cells. "In general, downregulation of ZEB1, RECK, TGFBR2 and BMPR2, as well as upregulation of CDK4, CCNE2, EZH2 and DNMT1 has been shown in lung adenocarcinoma and/or squamous cell carcinoma." (PMID 27588394, 2016).
Myocardial fibrosis (2 papers, 2021 to 2024). "Prior studies have shown that ferulic acid attenuates the migratory and proliferative capacity of cardiac fibroblasts and reduces myocardial fibrosis after myocardial infarction by inhibiting the pRB-E2F1/CCNE2 and RhoA/ROCK2 pathways." (PMID 38254195, 2024). "Following these findings, we assumed that MFA attenuated proliferation and migration ability of HCFs and thus attenuated myocardial fibrosis by suppressing the pRB-E2F1/CCNE2 and the RhoA/ROCK2 pathway." (PMID 34483923, 2021). "With these findings, we concluded that MFA suppressed proliferation and migration ability of HCFs and hence attenuated myocardial fibrosis, the mechanism of that was by suppressing the RB-E2F1/CCNE2 and the RhoA/ROCK2 pathway." (PMID 34483923, 2021).
myocardial infarction (2 papers, 2021 to 2024). Gross necrosis of the myocardium, as a result of interruption of the blood supply to the area, as in coronary thrombosis. "Finally, to elucidate the mechanism of phenomenon we observed, we found that MFA attenuated HCF differentiation after myocardial infarction by suppressing the migration and proliferation in HCFs, which was by suppressing the pRB-E2F1/CCNE2 and the RhoA/ROCK2 pathway." (PMID 34483923, 2021).
pancreatic adenocarcinoma (2 papers, 2020 to 2022). "Silibinin caused G1 arrest by decreasing the expression of Cyclin D1, Cyclin E2 and CDK4 and inducing increased expression of p21 and p15 in the human pancreatic adenocarcinoma cell line SW1990." (PMID 35401195, 2022). "The result showed that CCNE2 was specifically up‐regulated in ductal type of pancreatic adenocarcinoma, compared with that of other types of pancreatic adenocarcinoma (P = .0016)." (PMID 32141702, 2020). "All these results indicated that CCNE2 was correlated with clinical outcome of patients with pancreatic adenocarcinoma and might be a possible therapeutic target in the treatment of pancreatic adenocarcinoma." (PMID 32141702, 2020). "Besides, CCNE2 expression was also significantly higher in pancreatic adenocarcinoma of grade II/III than that of pancreatic adenocarcinoma of grade I (P = .0184)." (PMID 32141702, 2020). "Importantly, CCNE2 expression was negatively correlated with prognosis of overall survival probability of patients with pancreatic adenocarcinoma (P = .011)." (PMID 32141702, 2020). "Interestingly, CCNE2 expression was negatively correlated with clinical outcomes and grades of pancreatic adenocarcinoma." (PMID 32141702, 2020). "To confirm this hypothesis, we analysed the correlations of CCNE2 expression and clinical outcome of patients with pancreatic adenocarcinoma in the TCGA database." (PMID 32141702, 2020).
Rb (2 papers, 2022 to 2023). "HDAC9 expression is associated with cell proliferation in vitro, and its inhibition with cell arrest in the G1 phase is consistent with the reduction of Cyclin E2 and CDK2 expression in retinoblastoma cells." (PMID 37887350, 2023).
Adult T-cell leukemia (1 paper, 2020). "Conversely, ATF3 could also promote proliferation of Adult T-cell leukemia (ATL) cells via mechanisms including upregulation of CDC2 and cyclin E2." (PMID 32398095, 2020).
alveolar rhabdomyosarcoma (1 paper, 2022). A rapidly growing malignant mesenchymal neoplasm. "We did not observe a similar increase in adavosertib IC50 dose or CCNE2 mRNA expression in A673 (ES, EWSR1-FLI1+) and RH41 (alveolar rhabdomyosarcoma, PAX3-FOXO1+) cells upon CCNE1 KD." (PMID 35315355, 2022).
Azoospermia (1 paper, 2020). Absence of any measurable level of sperm,whereby spermatozoa cannot be observed even after centrifugation of the semen pellet. "Some target genes of the downregulated miRNAs, such as ACVR2A, CCND1, CCNE2, HMGA2, BMI1, NR2C2 and BCL2, have been associated with gonadal development, and germ cell maintenance through different pathways which could be relevant to the molecular mechanisms affected in KS patients with azoospermia." (PMID 32651451, 2020).
COVID-19 (1 paper, 2022). A disease caused by infection with severe acute respiratory syndrome coronavirus 2. "The molecular network analysis using Cytoscape highlighted seven core targets of curcumol, namely, AURKA, CDK1, CCNB1, CCNB2, CCNE1, CCNE2, and TTK in COVID-19 and LUAD." (PMID 35520289, 2022). "The network pharmacology analysis identified seven core targets (namely, AURKA, CDK1, CCNB1, CCNB2, CCNE1, CCNE2, and TTK) of curcumol in patients with COVID-19 and LUAD." (PMID 35520289, 2022). "We identified seven core pharmacological targets of curcumol, namely, AURKA, CDK1, CCNB1, CCNB2, CCNE1, CCNE2, and TTK, in treating LUAD and COVID-19." (PMID 35520289, 2022).
cystic fibrosis (1 paper, 2017). Autosomal recessive disorder caused by pathogenic variants in the CFTR gene (cystic fibrosis transmembrane conductance regulator), which encodes a chloride and bicarbonate channel expressed in epithelial cells, and follow the diagnosis criteria. "We found that IFI16, CCNE2 and IGFBP2 are potential modifiers in the altered lung function in Cystic Fibrosis." (PMID 28339466, 2017).
diabetes (1 paper, 2023). "The role of hsa-miR-503 in pathomechanism of diabetes complications depends on mitochondrial activity (DHFR), cell cycle control (CCNE2), cell protection (SOD2), podocyte migration (ANLN), inflammatory process (IL10, EFE2, VEGFA) and fibrosis (COL1A1), showing its contribution to CKD development." (PMID 36859746, 2023).
fibrosis (1 paper, 2019). the formation of excess fibrous connective tissue in an organ or tissue in a reparative or reactive process. "According to our KEGG pathway enrichment results, the cell cycle pathway is uniquely enriched in HBV-related fibrosis dataset, with CcnE2 being significantly up-regulated only in this HBV dataset, but not in the HCV or NAFLD datasets." (PMID 30923657, 2019).
follicular lymphoma (1 paper, 2013). Follicular lymphoma is a form of non-Hodgkin lymphoma characterized by a proliferation of B cells whose nodular structure of follicular architecture is preserved. "Aggressive follicular lymphoma, a subset of NHL, is associated with upregulation of genes involved in cell cycle control such as CCNE2 (cyclin E2), CCNA2 (cyclin A2), CDK2 (cyclin-dependent kinase 2), and genes-reflecting increased metabolism and DNA synthesis." (PMID 23533401, 2013).
HCMV infection (1 paper, 2010). "Crucially, we demonstrate that targeting of cyclin E2 by miR-US25-1 occurs in the context of HCMV infection and results in inhibition of cyclin E2 protein expression." (PMID 20585629, 2010). "Furthermore, as is the case with cyclin E1, cyclin E2 levels were induced by HCMV infection in all serum conditions." (PMID 20585629, 2010).
Hypertension (1 paper, 2024). The presence of chronic increased pressure in the systemic arterial system. "The risk of hypertension is related to the NRBP1, REG4, CCNE2, and KCNJ11 genes." (PMID 38915894, 2024).
latent infection (1 paper, 2023). "The cell proliferation marker MKI67 as well as genes involved in G1-S and G2-M transition, such as CDK1, CDK2, CCNE2, PRIM2, AKT1, and FOXM1, were significantly downregulated in latent infection compared to actively infected cells." (PMID 38038477, 2023).
male infertility (1 paper, 2010). The inability of the male to effect fertilization of an ovum after a specified period of unprotected intercourse. "In addition, cyclin E1+/- E2-/- mice display more pronounced testicular hypoplasia and male infertility than cyclin E2-/- mice, indicating that it is unlikely that excess cyclin E1 causes this phenotype, as the phenotype is more severe when a cyclin E1 allele is removed." (PMID 20180967, 2010). "Of interest, cyclin E2, but not cyclin E1, is upregulated by the p110 isoform of the transcription factor CDP/Cux and CDP/Cux knockout mice also suffer from male infertility, although without testicular atrophy." (PMID 20180967, 2010).
metastatic tumor (1 paper, 2021). "Cox proportional hazard regression analysis of PFS according to cyclin E2 expression levels and clinicopathologic characteristics, including age at metastatic disease and site of relapse, showed that cyclin E2 was an independent prognostic factor for PFS." (PMID 33602273, 2021).
multiple myeloma (1 paper, 2014). "In conclusion, in the vincristine-resistant U-266 multiple myeloma cell line, cyclin E2 gene expression was drastically increased, whereas ceramide metabolism genes were altered only in melphalan resistance in favor of survival in the U-266 cell line." (PMID 25330516, 2014).
periodontitis (1 paper, 2024). An acute or chronic inflammatory process that affects the tissues that surround and support the teeth. "For instance, PRF serum up-regulated genes such as CCNE2 and CDC25A linked to the cell cycle, as well as DKK1, a WNT-signaling antagonist with a potential impact on inflammatory osteolysis in rheumatoid arthritis and in periodontitis." (PMID 39120336, 2024).
renal cell cancer (1 paper, 2026). "According to bioinformatics analysis, the lncRNA embigin pseudogene 1 (EMBP1) acts as a ceRNA in renal cell cancer via the EMBP1/miR-9-5p/cyclin E2 (CCNE2) axis." (PMID 41431719, 2026). "In accordance with these findings, renal cell cancer tumorigenesis may be promoted by dysregulation of the EMBP1/miR-9-5p/CCNE2 axis." (PMID 41431719, 2026).
serous ovarian cancer (1 paper, 2020). "Cyclin E1 drives polyploidy in high-grade serous ovarian cancer in association with CCNE1 gene amplification and is generally associated with genome doubling, but cyclin E2 has not been reported in this context." (PMID 32823571, 2020).
Testicular atrophy (1 paper, 2010). Wasting (atrophy) of the testicle (the male gonad) manifested by a decrease in size and potentially by a loss of fertility. "A further unique phenotype of the cyclin E2 knockout mice is testicular atrophy and reduced male fertility, associated with aberrant meiosis." (PMID 20180967, 2010).
type 2 diabetes (1 paper, 2023). "Ten VAT-specific candidate genes were associated with type 2 diabetes after Bonferroni correction, including five causal genes supported by SMR and co-localisation: PABPC4 (1p34.3); CCNE2 (8q22.1); HAUS6 (9p22.1); CWF19L1 (10q24.31); and CCDC92 (12q24.31)." (PMID 37540242, 2023). "Besides, genetically elevated expression of CCNE2 on 8q22.1, HAUS6 on 9p22.1, CWF19L1 on 10q24.31, CCDC92 on 12q24.31 and DNAH10OS on 12q24.31 showed protective effects on type 2 diabetes risk." (PMID 37540242, 2023). "The effects of two other causal genes, CCNE2 and HAUS6, on type 2 diabetes have not been validated in functional studies and will need to be investigated in future research." (PMID 37540242, 2023).